WT1 (WT1 transcription factor)
Diseases named in the same sentence as WT1 in open-access papers (continued):
Sharing a sentence is not in itself a finding about the gene and the disease.
hypospadias (12 papers, 2012 to 2025). Hypospadias is the displacement of the urethral meatus on the ventrum of the penis. "Roughly, 15% of WT in children are syndromic; however, only one adult with WT was identified to have a WT1 germline mutation and one adult WT was revealed in a patient with cryptorchidism and hypospadias." (PMID 39148862, 2024). "WT1 SNPs have been associated with all types of hypospadias, and a significantly increased risk associated with SNPs was found for severe hypospadias." (PMID 33312738, 2020). "19q13.11 deletions and the Wilms tumor interacting protein (WTIP) gene result in hypospadias, making it a possible reason for this genital abnormality due to its well-known interaction with WT1." (PMID 40290553, 2025). "In this study, all exons and introns surrounding exons in the WT1 gene of 74 patients with hypospadias at a single facility were analyzed using Sanger sequencing." (PMID 38877226, 2024). "We also identified SROs overlapping with the following genes with established associations with hypospadias: RBFOX2, SHH, and WT1." (PMID 35457073, 2022). "In addition, several genes, such as SRY type HMG box9 (SOX9), HomeoboxA13 (HOXA13), Wilms tumor 1 (WT1) and mastermind-like domain-containing 1 (MAMLD1) are reported to be associated with hypospadias." (PMID 23272655, 2012).
neuroblastoma (12 papers, 2005 to 2025). Neuroblastoma (NB) is the most common solid, extracranial childhood tumor. "In difficult cases, next generation (targeted) sequencing can be performed including genes frequently mutated or altered in WTs (e.g., WTX, WT1, CTNNB1, SIX1, SIX2, miRNA processing genes) and neuroblastomas (PHOXB2, ALK, ARID1A/B genes)." (PMID 32204536, 2020). "In the present study, it has been investigated the expression pattern of WT1 isoforms in an in vitro model of neuroblastoma consisting in undifferentiated or all-trans retinoic acid (RA) differentiated cells." (PMID 27014421, 2016). "In the present study, therefore, it has been analyzed for the first time the expression pattern of WT1 proteins in undifferentiated and all-trans retinoic acid (RA) differentiated neuroblastoma cells in order to evaluate their involvement in tumor malignancy." (PMID 27014421, 2016). "This is consistent with the evidence that WT1 expression is greater in ganglioneuroma versus neuroblastoma." (PMID 27014421, 2016). "In this regard, it has been analyzed WT1 proteins in undifferentiated or RA differentiated neuroblastoma cells." (PMID 27014421, 2016). "Interestingly, CREB1 was consistently expressed at higher levels in neuroblastoma compared to the other tissues, and WT1 was expressed at lower levels in neuroblastoma compared to most of the adult cancer cohorts." (PMID 33918978, 2021). "A recent study has found that WT1 expression is inversely correlated with MYCN expression in neuroblastoma, confirming our findings in this study, and whilst a mechanistic link is unclear, an association between high WT1 expression and poor outcome in non-MYCN amplified neuroblastomas was observed." (PMID 33918978, 2021). "Interestingly, upon examination of other known ODC1 transcriptional regulators, we found that CREB1 was expressed at higher levels in neuroblastoma compared to other adult tumor types, whereas WT1 was expressed at lower levels." (PMID 33918978, 2021). "Blastemal type WTs and neuroblastomas are both positive for CD56, but WT1 is negative in neuroblastoma, while synaptophysin, chromogranin A, NB84, and PHOX2B are positive in neuroblastoma." (PMID 32204536, 2020). "Neuroblastomas are positive for neuroendocrine markers and negative for CK, WT1, and desmin." (PMID 34193155, 2021). "However, data regarding the expression profile of WT1 isoforms in neuroblastoma cells have not yet been described." (PMID 27014421, 2016). "This confirms previous data which have suggested that WT1 is not related to their oncogenicity and, instead, it might promote trans-differentiation of NB into a more benign ganglioneuroma/ganglioneuroblastoma." (PMID 27014421, 2016).
cervical cancer (11 papers, 2012 to 2025). A primary or metastatic malignant neoplasm involving the cervix. "The case underlines that adenosarcoma can masquerade as cervical cancer, emphasises the need for generous tissue sampling and WT1/ER-based immunohistochemistry to define tumour origin, and confirms excellent outcomes with complete surgical excision for stage I disease." (PMID 41624694, 2025). "MAP4K4 and WT1 contribute to SOX6‐induced cellular senescence in cervical cancer by synergistically activating the ATF2–TGFβ2–Smad2/3 signaling pathway." (PMID 38383842, 2024). "In summary, this study found that MAP4K4 and WT1 contributed to SOX6‐induced cellular senescence in cervical cancer by synergistically activating the ATF2–TGFβ2–Smad2/3 signaling pathway." (PMID 38383842, 2024). "Ourresults indicate that methylation in the WT1 promoter regionincreases significantly in cervical cancer and high-grade squamous intraepitheliallesions in comparison to normal cervical tissues of Uygur women in Xinjiang." (PMID 29658966, 2018). "The methylation rate of WT1 in normal cervical tissues, CINtissues and cervical cancer tissues was 7.0, 36.7 and89.6%, respectively." (PMID 29658966, 2018). "The use of differential methylation hybridization using a pilot methylation array allowed the identification of SOX1, NKX6-1, PAX1, WT1, and LMX1A as frequently methylated genes in cervical cancer and precursor lesions." (PMID 34790573, 2021). "We aimed to understand the expression of WT1,NKX6-1 and DBC1 in the cervical cancer of Uygur womenin Xinjiang, and the potential of methylation markers for the screening of cervicalcancer." (PMID 29658966, 2018). "Our findings indicated thatmethylation in the promoter regions of WT1, NKX6-1 andDBC1 is correlated with cervical cancer tumorigenesis inUygur women." (PMID 29658966, 2018). "In previous studies, we discovered that SOX1, NKX6-1, PAX1, WT1, and LMX1A are highly methylated in cervical cancer." (PMID 22815913, 2012). "The differential methylation hybridization (DMH) using a pilot methylation array identified SOX1, NKX6-1, PAX1, WT1, and LMX1A as frequently methylated genes in cervical cancer and its precursor lesions." (PMID 22815913, 2012). "We assessed the expression of WT1, AGT, MIEN1 and SPOUTY4 across cervical cancer tissues via IHC." (PMID 38028542, 2023). "Furthermore, WT1, NKX6-1 andDBC1 genes were hypermethylated in the high-grade squamousintraepithelial lesion (CIN2, CIN3) and in the cervical cancer tissues withinfection of HPV16/18 (both P< 0.05)." (PMID 29658966, 2018). "Of the 53 differentially methylated candidates that were found in both ADC and SCC, 20 genes were described previously in literature as being more frequently methylated in cancer, and 6 genes in (squamous-cell) cervical cancer (SOX1, SOX14, ONECUT1 and WT1) or high-grade CIN (GFRA1, SOX1 and TBX20)." (PMID 27738327, 2016). "The expression of WT1, NKX6-1 andDBC1 genes in methylation-positive cervical cancer tissues wassignificantly lower than in methylation-negative normal cervical tissues." (PMID 29658966, 2018). "We analyzed statistically the relationship of themethylation rates of WT1, NKX6-1 and DBC1 withpatient age and the staging of the International Federation of Gynecology andObstetrics (FIGO), in 48 cervical cancer tissues; there was no statisticallysignificant difference." (PMID 29658966, 2018).
clear cell carcinoma (11 papers, 2016 to 2025). "In females, this differential diagnosis is expanded to clear-cell carcinoma of the female genital (napsin A, WT1 and PR positive) tract and in males with clear-cell renal-type prostatic acinar adenocarcinoma (AMACR- and NKX3.1-positive)." (PMID 41562801, 2025). "WT1 is useful in distinguishing HGSCs and LGSCs from clear cell carcinomas (CCCs) and mucinous carcinomas (MCs); WT1 is diffusely expressed in most HGSCs and LGSCs, whereas it is negative in most CCCs and MCs." (PMID 39329907, 2024). "Of the 20 patients who were tested containing HNF1β, WT-1, ER, and PR, 11 (55%) had the combination of positive HNF1β, and negative WT-1, ER, and PR characteristics for the diagnosis of clear cell carcinoma." (PMID 33766002, 2021). "The results indicated that, in a highly heterogeneous set of 35 studies that compared endometrioid, serous, clear cells carcinoma and carcinosarcoma, the overall rate of WT1 expression was 25% (95% CI = 0.20–0.30; Q = 120.4; I2 = 71.7), with p < 0.05." (PMID 32859123, 2020). "In clear cell carcinoma, the patterns of detection of oestrogen receptor (ER), HNF1β and WT1 were also similar to the original tumour, despite variations in intensity." (PMID 33173111, 2020). "PAX8 is positive in most ovarian nonmucinous surface epithelial tumors: serous, clear cell, and endometrioid cell types, especially for endometrioid and clear cell carcinoma, in which WT1 is generally negative or only focally positive." (PMID 27047697, 2016). "The absence of both WT1 and PgR positivity suggests mucinous or clear cell carcinoma." (PMID 38573494, 2024). "However, the tumor was negative for PAX8, WT-1, ER, and PR and showed only focal positivity for EMA, which is inconsistent with the typical immunophenotype of clear cell carcinoma." (PMID 41149460, 2025).
Hypertension (11 papers, 2016 to 2025). The presence of chronic increased pressure in the systemic arterial system. "Our observations confirm that children with SRNS carrying WT1 exonic variants quite often present with hypertension and lack edemas, which may help to distinguish them from patients with the other monogenic causes of SRNS." (PMID 35610319, 2022). "Moreover, WT1 has also been involved in cardiac development and disease, a link that was further supported by our phenome-wide association look-up results, since this region was associated with hypertension and cardiovascular disease." (PMID 35739095, 2022). "Interestingly, inherited mutations in the WT-1 gene can lead to life-threatening hypertension." (PMID 27009470, 2016). "Moreover, the decoupling between Hsp70 and VDR associated with a possible poor expression of WT-1 could be keys to hypertension development." (PMID 27009470, 2016). "Therefore, altered mitochondrial energy metabolism linked to master nephrogenic factors, such as WT-1, could play a central role in the essential hypertension model, and should be further investigated." (PMID 27009470, 2016). "In addition, we discuss the possibility that mitochondrial injury and dysfunction linked to master nephrogenic factors, such as WT-1, could play a central role in the pathogenesis of the essential hypertension model." (PMID 27009470, 2016). "Mutations or dysregulation of WT1 were further linked to elevated REN expression, hypertension, and exacerbated tumor progression." (PMID 40534868, 2025). "Intriguingly, REN transcription has been shown to be regulated by the WT1 gene (specifically the WT1-KTS isoform), which is frequently mutated in WT patients and associated with elevated plasma renin levels and hypertension." (PMID 40534868, 2025). "The aim of this paper is to evaluate the expression of WT-1 and related genes in the nephrogenic process in connection with the development of hypertension as well as the corresponding anatomical and functional correlation." (PMID 27009470, 2016). "In summary, children with SRNS and a pathogenic variant in the WT1 gene frequently presented with hypertension and a lack of edemas." (PMID 35610319, 2022). "While edema, a diagnostic criterion of NS, was missing in 44% (4/9) of the studied patients with exonic WT1 variants, hypertension, a hugely non-specific symptom, was also detected in 44% (4/9) of these patients." (PMID 35610319, 2022). "If so, this may suggest that deregulation in the expression of WT-1 and its impact on nephrogenesis induction could be crucial in understanding the development and maintenance of hypertension." (PMID 27009470, 2016). "Recent evidences suggest that alterations in key nephrogenic factors, such as Wilms’ tumor 1 transcription factor (WT-1), could contribute to the development of hypertension." (PMID 27009470, 2016). "Hence, kidney impairment is a significant event in hypertension development and, thus, alteration of a key nephrogenic gene expression such as WT-1 appears to contribute to hypertension development." (PMID 27009470, 2016). "Kidney damage is a significant event in the development of hypertension and, thus, maternal food restriction alters key fetal nephrogenesis gene expression, such as Wilms’ tumor transcription factor 1 (WT-1) and other factors; this appears to contribute to hypertension development." (PMID 27009470, 2016). "However, this is the first study using the essential hypertension model which established a lesser WT-1 expression level occurring parallel to renal morphometric changes during late renal development and its consolidation as an adult organ." (PMID 27009470, 2016). "Indeed, WT1-targeted T cells were shown to target healthy renal cells (which express WT1), and NY-ESO-1 vaccination induced multiple adverse events such as anorexia, hypertension, lung injury, vomiting, abdominal pain, and rash." (PMID 37582761, 2023).
Hypertension (continued). "One patient died due to an unknown cause, possibly due to underlying medical conditions of hypertension and thrombosis; this fatal SAE was assessed by the investigators as not causally related to WT1-immunotherapeutic administration." (PMID 28176175, 2017).
metastatic tumors (11 papers, 2017 to 2025). "Sanger sequencing of the PCR products further validated the precise joining of EWSR1 exon 7 to WT1 exon 8 in RNA transcripts from both the primary and metastatic tumor samples." (PMID 37457440, 2023). "Similar to the primary tumors, PTU metastatic tumors were positive for Ki-67, γH2AX, WT1, and Pan-Keratin." (PMID 35173307, 2022). "Comparing cell lines regarding their isolation site, a statistically significant (p = 0.004) difference in WT1 promoter methylation was found between cell lines stemming from primary versus metastatic tumors." (PMID 32605217, 2020). "Unexpectedly, these include Wt-1 and Axl; both are important as drivers of human metastatic disease." (PMID 31428571, 2019). "MPM is mainly distinguished from metastatic disease by calretinin, CK 5/6, WT-1 and D2-40." (PMID 36557076, 2022). "Using qPCR primers in the C-terminus of WT1, we found a slight increase in the expression of EWSR1-WT1 in the recurrent/metastatic tumor as compared to the primary tumor (∆∆Cq of 0.30)." (PMID 37457440, 2023). "The pathological and immunohistochemical findings in our case, including positive staining for calretinin, D2-40, CK7, BAP1, and WT1, and negativity for various other markers, confirmed the diagnosis of a benign cystic adenomatoid tumor and ruled out metastatic disease." (PMID 39479461, 2024).
kidney cancer (10 papers, 2010 to 2024). Primary or metastatic malignant neoplasm involving the kidney. "Similarly, Wt1 was initially identified as a tumor-suppressor gene mutated in the rare pediatric kidney cancer Wilms’ Tumor50." (PMID 31511511, 2019). "Improper splicing, a mechanism that contributes to dysregulation of the Wilms tumor suppressor gene WT1, might also contribute to the observed downregulation of SOSTDC1 in kidney cancer." (PMID 21080955, 2010). "All in all, the documented immunoexpression patterns for WT1 and TDs in RCC tumor cells, TMS, and tumor-adjacent HRT generate numerous hypotheses about the origins and biology of RCCs and, potentially, may even inform kidney cancer therapeutics." (PMID 38929778, 2024).
soft tissue sarcoma (10 papers, 2010 to 2025). A malignant neoplasm arising from muscle tissue, adipose tissue, blood vessels, fibrous tissue, or other supportive tissues excluding the bones. "An increasing number of results strongly indicate that WT1 gene is also involved in tumorigenesis of various types of human bone and soft-tissue sarcomas." (PMID 28107196, 2017). "WT1 peptide immunotherapy has no significant side effects other than localized skin erythema and is more promising in aspect that soft tissue sarcomas are more common in childhood." (PMID 25026998, 2014). "Our data indicated that the cytoplasmic WT1 expression may have prognostic significance in high grade STS and various kinds of soft tissue sarcomas are candidates for WT1 targeted immunotherapy." (PMID 25026998, 2014). "Twenty-nine datasets reported an adverse impact of WT1 positive expression on prognosis regardless of the statistic power, while, 3 datasets (2 for NSCLC and 1 for soft tissue sarcoma) reported opposite results." (PMID 25748047, 2015).
gastric cancer (9 papers, 2015 to 2025). A primary or metastatic malignant neoplasm involving the stomach. "Serum WT1–271 IgM antibodies exhibit high sensitivity for early-stage gastric cancer and can serve as a diagnostic marker for gastric cancer when combined with autoantibody screening, especially in the early stages." (PMID 41357197, 2025). "Hypomethylation of the CpG site cg06516124 can increase the expression level of WT1 and is significantly associated with increased gastric cancer risk." (PMID 40177272, 2025). "Vaccination with autologous DCs induced a significant CD8+ T-cell response against WT1 in patients with ovarian, breast, and gastric cancer who presented with a WT1 mutation (p < 0.05)." (PMID 34207103, 2021). "Of the four patients completing one course of WT1-DCs vaccination three had gastric cancer and one had salivary gland cancer." (PMID 32231023, 2020). "Furthermore, our findings suggest that RV Wt1-5 has the potential to reactivate the immune system within tumor tissue, making it a potential candidate for virotherapy in gastric cancer." (PMID 37186587, 2023). "To further examine the induction of TAA-specific memory T cells by ZSTK474 in cancer settings, we used PBMCs from three gastric cancer patients who exhibited humoral immune responses against WT-1, NY-ESO-1, MAGE-A3 or MAGE-A4 that were expressed by their own tumors." (PMID 34446575, 2021). "WT1-CTLs from three male patients with gastric cancer were detected using WT1-tetramer analysis." (PMID 32231023, 2020).
synovial sarcoma (9 papers, 2018 to 2025). "However, an important point differentiating synovial sarcoma from MM is negative WT1, with a t(X; 18) or SS18-SSX gene fusion." (PMID 38938650, 2024). "No expression of Desmin, SMA, CD31, Caldesmon, TLE-1, WT-1, and SS18 was in the tumor, which could be differentiated from synovial sarcoma." (PMID 40831926, 2025).